EEF1A1P5 (eukaryotic translation elongation factor 1 alpha 1 pseudogene 5)
Description:
This protein promotes the GTP-dependent binding of aminoacyl-tRNA to the A-site of ribosomes during protein biosynthesis.
Synonyms: formerly EEF1AL3
Gene: Processed pseudogene on chromosome 9 (133,019,486 to 133,020,874, forward strand). Ensembl gene ENSG00000196205.
Subcellular location: Cytoplasm
Diseases named in the same sentence as EEF1A1P5 in open-access papers:
EEF1A1P5 is named in the same sentence as 1 disease in open-access papers, as found by Europe PMC text mining. Sharing a sentence is not in itself a finding about the gene and the disease. The quoted sentences say what the papers report.
tumor (1 paper, 2023). "However, there is evidence that EEF1A1P5 gene transcripts and the RPLP0P6 protein are present in exosomes of various tumor cell lines." (PMID 37298233, 2023).